VPS25 (vacuolar protein sorting 25 homolog)
Diseases named in the same sentence as VPS25 in open-access papers:
VPS25 is named in the same sentence as 14 diseases in open-access papers, as found by Europe PMC text mining. Sharing a sentence is not in itself a finding about the gene and the disease. The quoted sentences say what the papers report.
glioma (9 papers, 2021 to 2024). A benign or malignant brain and spinal cord tumor that arises from glial cells (astrocytes, oligodendrocytes, ependymal cells). "We found that the expression of VPS25 was upregulated in glioma and associated with poor prognosis of glioma patients." (PMID 34863175, 2021). "Here, we determined that the VPS25 deficiency significantly inhibited glioma cell proliferation by inducing the G0/G1 phase arrest of the cell cycle." (PMID 34863175, 2021). "Finally, YTHDC1 inhibits cell proliferation by reducing the expression of Vacuolar protein-sorting-associated protein 25 (VPS25), which is highly expressed in gliomas and augments proliferation through targeting JAK-STAT signaling." (PMID 35625706, 2022). "In WHO II and III grade glioma, the VPS25 expression in IDH-mutated is higher than in IDH-wildtype." (PMID 34863175, 2021). "Therefore, we investigated whether the upregulation of VPS25 in glioma was associated with the m6A modification." (PMID 34863175, 2021). "Zhu el al reported YTHDC1-mediated VPS25 regulated the cell cycle by activating the JAK-STAT signaling pathway in human glioma cells." (PMID 38978074, 2024). "VPS25 was upregulated in glioma tissues, and it was correlated with poor prognosis in glioma patients." (PMID 37601252, 2023). "An important example is the investigation of activators of the JAK/Stat pathway such as Runx1 and VPS25, which are overexpressed in glioma tissues and thus serve as potential therapeutic targets." (PMID 37626776, 2023). "The resent research shown that YTHDC1-mediated VPS25 regulates cell cycle by targeting JAK-STAT signaling in human glioma cells." (PMID 35935338, 2022). "VPS25 was upregulated in glioma tissues, which was correlated with poor prognosis in glioma patients." (PMID 34863175, 2021). "Then we employed another independent VPS25 siRNA (siVPS25-1) to detect the function of VPS25 in glioma." (PMID 34863175, 2021). "Compared with the normal brain tissues, the VPS25 expression was significantly increased in glioma tissues." (PMID 34863175, 2021). "We also demonstrated that YTHDC1 affects the proliferation of glioma cells by regulating VPS25 expression." (PMID 34863175, 2021). "Meanwhile, VPS25 induced a G0/G1 phase arrest of the cell cycle in glioma cells by directly mediating p21, CDK2, and cyclin E expression, and JAK-signal transducer and activator of transcription (STAT) activation." (PMID 34863175, 2021). "The RT-qPCR analysis revealed that transfection of glioma cells with siVPS25-3 significantly decreased the expression of VPS25 by 95% in U87MG and 83% in U251." (PMID 34863175, 2021). "We found that the glioma cells under-expressing VPS25 were arrested at the G0/G1 phase, with a corresponding decrease in the percentage of cells in the G2/M phase." (PMID 34863175, 2021). "To figure out the mechanism of VPS25-regulated cell proliferation, we used flow cytometry to detect glioma cell apoptosis." (PMID 34863175, 2021). "To investigate the mechanism of VPS25 in glioma, we detected the DEG in VPS25-silenced U251 cells by RNA-seq." (PMID 34863175, 2021). "After that, we determined the expression level of VPS25 in normal brain (n = 14) and glioma tissues (n = 66) collected from Yijishan Hospital by RT-qPCR." (PMID 34863175, 2021). "Additionally, YTHDC1 influences glioma cell proliferation through its impact on VPS25, a protein upregulated in gliomas." (PMID 38474421, 2024). "VPS25 is highly expressed in glioma and increases proliferation via JAK-STAT signalling." (PMID 37444417, 2023). "Then, VPS25 siRNA was transfected to reduce the intracellular mRNA level of glioma." (PMID 34863175, 2021). "We found that VPS25 is overexpressed in glioma and promotes the proliferation of glioma." (PMID 34863175, 2021). "To verify the hypothesis that VPS25 functions as a candidate promoter in glioma, we examined the effect of VPS25 expression on cell proliferation and colony formation." (PMID 34863175, 2021).
glioma (continued). "In summary, we determined the VPS25 expression and its biological function in glioma." (PMID 34863175, 2021). "The expression of VPS25 was significantly increased in glioma vs. controls." (PMID 34863175, 2021). "To further elucidate whether VPS25 mediates proliferation through the JAK-STAT pathway, we overexpressed VPS25 in the glioma cells." (PMID 34863175, 2021). "Taken together, these results provided evidence that VPS25 upregulation may play an important role in the development of glioma." (PMID 34863175, 2021). "In conclusion, these findings indicated that knockdown of VPS25 suppresses glioma growth in vivo." (PMID 34863175, 2021). "We then speculated that METTL3, METTL14, and YTHDC1 might affect the proliferation of glioma cells through VPS25." (PMID 34863175, 2021). "Furthermore, VPS25 knockdown inhibited the proliferation, blocked the cell cycle, and promoted apoptosis in glioma cells." (PMID 34863175, 2021). "VPS25 was also necessary for glioma cells' proliferation, cell cycle, and apoptosis." (PMID 34863175, 2021). "Together, these results indicate that YTHDC1 may inhibit glioma proliferation by reducing VPS25 expression." (PMID 34863175, 2021). "We further investigated the mechanism by which VPS25 promotes glioma progression." (PMID 34863175, 2021). "Thus, this study not only elucidates the VPS25-dependent regulation of glioma but also provides a new putative biomarker and therapeutic target for glioma diagnosis and treatment." (PMID 34863175, 2021). "However, YTHDC1 was reported to suppress the progression of glioma by inhibiting VPS25." (PMID 35974388, 2022). "Finally, YTHDC1 inhibited glioma proliferation by reducing the expression of VPS25." (PMID 34863175, 2021). "The glioma patients including both lower grade glioma (LGG) and GBM with high VPS25 expression had a shorter survival time than those with low VPS25 expression." (PMID 34863175, 2021). "Combining the two databases, we noticed that MVB12A, VPS25, CHMP2A, and IST1 were highly expressed in glioma." (PMID 34863175, 2021). "RT-qPCR showed that VPS25 expression was significantly increased in glioma cell lines (U87MG and U251), compared with VPS25 expression measured in normal brain tissues." (PMID 34863175, 2021). "We decreased VPS25 expression in METTL3, METTL14, and YTHDC1 KD glioma cells, and a series of restoration assays were performed." (PMID 34863175, 2021). "Therefore, we speculate that VPS25 may function independently of the ESCRT complex in glioma." (PMID 34863175, 2021). "For instance, MVB12A, VPS25, CHMP2A, and IST1 were significantly upregulated in glioma, whereas VPS36 and CHMP1B were significantly downregulated." (PMID 34863175, 2021). "The mRNA level of VPS25 was upregulated in glioma cells with KD of METTL3 or METTL14, but it was not affected in the YTHDC1 KD cells." (PMID 34863175, 2021). "However, the protein level of VPS25 was not affected in glioma cells with KD of METTL3 or METTL14, but it was upregulated in the YTHDC1 KD cells." (PMID 34863175, 2021).
viral infection (3 papers, 2017 to 2022). "Collectively, our study proposed a novel mechanism by which EV71 3A protein interacts with a component of the ESCRT-II complex, VPS25 to mediate exosome biogenesis and the release of progeny EV71, leading to facilitating viral infection and replication." (PMID 36274707, 2022). "The protein levels of these ESCRT subunits (HRS, VPS28, VPS25, CHMP2B, CHMP4B, CHMP7, VPS4A and ALIX) in the VRC were significantly increased by the viral infection in a dose-dependent manner." (PMID 35120190, 2022).
type 2 diabetes (2 papers, 2017 to 2023). "Four mQTL tagging the CpGs cg08857797 (VPS25), cg00144180 (HDAC4), cg16765088 (SYNM) and cg25536676 (DHCR24) were suggestively associated with type 2 diabetes, with an unadjusted GWAS p<0.05." (PMID 37202507, 2023).
bladder cancer (1 paper, 2023). "In bladder cancer, we screened seven hub genes (ACLY, CNP, NKIRAS2, P3H4, PDIA6, VPS25 and XPO1) associated with survival." (PMID 37601252, 2023).
glioblastoma (1 paper, 2022). The most malignant astrocytic tumor (WHO grade IV). "In glioblastoma cells, VPS25 mediated the phosphorylation of Janus kinase (JAK) and signal transducers and activators of transcription (STAT) proteins, and activates this pathway." (PMID 36012529, 2022).
prostate carcinoma (1 paper, 2023). A carcinoma that arises from epithelial cells of the prostate gland. "Taken together, given its small size yet excellent predictive power, we concluded [AQP1, SEPT8, RBM17, TRIM47, VPS25] as a novel, practical biomarker panel for predicting response to 17-AAG treatment in prostate cancer." (PMID 36743211, 2023).
tumor (15 papers, 2009 to 2026). "Collectively, these results indicate that high VPS25 expression in cancer cells is associated with an immunosuppressive tumor microenvironment within HNSCC, highlighting the immunosuppressive role of VPS25high cancer cells." (PMID 40149859, 2025). "To further delineate the association between VPS25 and tumor-infiltrating immune cells, we performed IHC staining on our TMAs." (PMID 40149859, 2025). "Several tumor models in Drosophila (RasV12scrib, RasV12, vps25) recruit hemocytes to overgrowing tumor tissues, with parallels to mammalian TAMs." (PMID 41542540, 2026). "Although previous studies have indicated a tumor-suppressive role for VPS25, our current research reveals that VPS25 is significantly upregulated in HNSCC cells and correlates with poor clinical outcomes." (PMID 40149859, 2025). "Spatial transcriptomics also demonstrated a direct association between VPS25 and PVR expression in tumor regions." (PMID 40149859, 2025). "Our findings underscore the multifaceted involvement of VPS25 in tumor progression, highlighting the need for further in-depth investigations into its mechanisms of action." (PMID 40149859, 2025). "Secondly, scRNA-seq analyses revealed that VPS25 overexpression drives tumor cell proliferation and migration, which was further validated through in vitro knockdown experiments using CAL27 cells." (PMID 40149859, 2025). "VPS25 has also been described as a tumor suppressor in Drosophila, where it prevents neoplastic transformation by regulating endocytic trafficking, thereby maintaining proper epithelial organization and preventing metastasis." (PMID 40149859, 2025). "Single-cell RNA sequencing of tumor tissues and VPS25 knockdown experiments in CAL27 cells were used to investigate its biological functions." (PMID 40149859, 2025). "Future research should focus on experimentally validating the molecular mechanisms by which VPS25 modulates tumor immunology." (PMID 40149859, 2025). "Further bioinformatic analyses and experimental studies demonstrated that VPS25 enhances tumor growth and migration, potentially through the regulation of DNA repair mechanisms." (PMID 40149859, 2025). "To evaluate the role of VPS25 in tumor immune checkpoint blockade (ICB) therapy, we investigated its impact on ICB efficacy." (PMID 40149859, 2025). "And found that except for VPS25, the other six genes were correlated with the tumor immune microenvironment." (PMID 37601252, 2023). "In this study, the overexpression of VPS25 in the high-risk group promoted the formation of ESCRT-II and delayed or prevented the necrotic apoptosis of tumor cells, thus contributed to worse OS in high-risk groups." (PMID 35672673, 2022). "We then checked the activity of JAK-STAT signaling by western blot in U87MG and U251 cells, as well as the VPS25 KD tumor tissue in vivo." (PMID 34863175, 2021). "Again, the overlap was minimal but among the top hits in both screens was the gene VPS25, which is a tumor suppressor known to inhibit the Notch pathway." (PMID 34049503, 2021). "Further analysis showed that the expression of VPS25 was increased in tissues with advanced tumor stage." (PMID 34863175, 2021). "The VPS25 expression in the xenograft tumor was then examined by western blot and immunohistochemistry." (PMID 34863175, 2021). "SR-BI removal led to the diminished expression of RAB22a, SNAP25 and VPS25, which suggested reduced generation and secretion of tumor-derived extracellular vesicles." (PMID 30823658, 2019). "In contrast, since the phenotype of vps25 ark double mutant discs is more severe than that of vps25 single mutant discs, apoptosis in these mutant discs serves as a tumor suppressor mechanism to eliminate the cancerous tissue." (PMID 23418496, 2013). "Additionally, by upregulating PVR expression in tumor cells, VPS25 activated the immunosuppressive PVR-TIGIT signaling axis, thereby facilitating immune evasion." (PMID 40149859, 2025).
tumor (continued). "Our investigation revealed an inverse correlation between VPS25 expression levels and tumor infiltration by immunostimulatory cells (CD8+ T cells, NK cells, B cells, and DCs), whereas a positive association was observed with immunosuppressive cell populations (MDSCs and M2-polarized macrophages)." (PMID 40149859, 2025). "As presented, VPS25 expression was downregulated in the VPS25-KD tumor group." (PMID 34863175, 2021). "In sheer contrast to these, a number of ESCRT-I, -II, -III mutations, such as those mapping to Tsg101, vps28, Vps25, vps20, when made homozygous in eye discs, display a Mutant Eye No Eclosion (MENE) phenotype that have been associated loss of tumor suppression in Drosophila." (PMID 24718108, 2014). "Thus, this study supports the idea that de-regulation of signaling pathways, especially JNK and JAK/STAT signaling, in vps22, vps25, and vps36 mutant tissues leads to neoplasia." (PMID 23418496, 2013). "To understand this tumor-like phenotype in more detail, we examined proliferation, cellular architecture, differentiation, and metastatic potential of eye-antennal discs predominantly mutant for vps22, vps25, or vps36." (PMID 23418496, 2013). "In Drosophila imaginal epithelia, cells mutant for the endocytic neoplastic tumor suppressor gene vps25 stimulate nearby untransformed cells to express Drosophila Inhibitor-of-Apoptosis-Protein-1 (DIAP-1), conferring resistance to apoptosis non-cell autonomously." (PMID 22679484, 2012). "Tissue predominantly mutant for vps25 displays neoplastic tumor characteristics." (PMID 19132102, 2009). "As certain endocytic tumor suppressors activate Notch (e.g. ept and vps25) and others do so to a much lesser extent (e.g. ayx7/avl), one way to begin to address this question may be to examine the pattern of Rbf1 expression in each of these mutant backgrounds." (PMID 19855819, 2009). "Additionally, targeting VPS25 may simultaneously disrupt tumor progression and enhance anti-tumor immunity." (PMID 40149859, 2025). "Therefore, vps22, vps25 and vps36 mutant discs display neoplastic tumor characteristics." (PMID 19132102, 2009). "A relatively small number of neoplastic tumour suppressor mutants have been described in Drosophila and, apart from the junctional/scaffold tumour suppressors of scrib, dlg and lgl, the other group of genes, Rab5, avl, erupted and vps25, regulate endocytic pathways." (PMID 19778415, 2009). "We then categorized patients based on VPS25 and KRT5 (tumor cell marker gene) expression into high-score and low-score groups." (PMID 40149859, 2025). "In conclusion, our findings highlight that elevated VPS25 expression serves as a strong predictor of unfavorable clinical outcomes in HNSCC, warranting further investigation into its role in tumor progression and potential therapeutic targeting." (PMID 40149859, 2025). "We found that a higher expression of VPS25 and CHMP2A was more frequent in tissues with advanced tumor stage from GEO and TCGA databases." (PMID 34863175, 2021). "Notably, we found that VPS25, a component of the ESCRT-II complex, was markedly overexpressed in HNSCC tumor tissues and correlated with poor overall survival." (PMID 40149859, 2025). "Exploring the role of VPS25 in other cancer types and its broader implications within the ESCRT pathway may provide a more comprehensive understanding of its functions in tumor biology." (PMID 40149859, 2025). "Studies in Drosophila have found that VPS25 is an unconventional tumor suppressor that prevents the non-autonomous hyperproliferation of cells by modulating NOTCH signaling." (PMID 34863175, 2021). "Thus ept and vps25 behave both as non-cell autonomous growth suppressors, and as conditional, cell-autonomous neoplastic tumor suppressors." (PMID 19787055, 2009).
infection (7 papers, 2017 to 2025). The state of being infected such as from the introduction of a foreign agent such as serum, vaccine, antigenic substance or organism. "In view of the close relationship of NLRX1, VPS25, and PIP4K2B with mitophagy, we speculate that PAstV/SH/2022/CM1 infection may cause mitochondrial injury—mitophagy—to resist the innate host immunity." (PMID 35891364, 2022).
cancer (4 papers, 2022 to 2025). A tumor composed of atypical neoplastic, often pleomorphic cells that invade other tissues. "Then, risk scores were calculated for every cancer sample calculated by using the following formula: Riskraw = DAD1*2.316+CYCS*1.426+CSNK2A2*1.576+VPS25*0.728+VDAC1*0.976+TMLHE*0.381+CYTH3*0.024+PRKCA*0.260-TP73*0.567+FZD6*0.047+SQSTM1*0.094-MAP2K7*3.070." (PMID 35185897, 2022). "In this study, we observed that VPS25 is highly expressed in cancer cell-enriched genes related to DNA repair, E2F targets, and G2M checkpoints, highlighting its essential role in proliferation and cell cycle progression." (PMID 40149859, 2025). "Our screen identified ATG9A along with several ESCRT genes (UBAP1, CHMP6, and VPS25) as critical determinants of the cancer cell response to macrophages." (PMID 40595560, 2025). "Remarkably, the CC3 subgroup exhibited a larger proportion of cancer cells with elevated VPS25 expression (VPS25high) compared to those with low VPS25 expression (VPS25low), suggesting that VPS25high cancer cells display enhanced invasive potential." (PMID 40149859, 2025). "The IHC results demonstrated strong cytoplasmic staining of VPS25 in HNSCC cancer cells, contrasting with minimal staining in epithelial cells of NOM." (PMID 40149859, 2025). "RNA sequencing of VPS25 KD cancer cells revealed enrichment in immunoregulatory pathways, encompassing immune activation, inflammatory processes, and cytokine-mediated signaling pathways." (PMID 40149859, 2025). "Mechanistically, we observed increased PVR expression in VPS25high cancer cells, and knockdown of VPS25 reduced PVR expression, suggesting that VPS25 may mediate immune evasion through the PVR-TIGIT axis." (PMID 40149859, 2025). "Among the seven functional subpopulations of cancer cells, the CC3 cluster exhibited the most elevated VPS25 expression levels." (PMID 40149859, 2025). "Pathway analysis for rituximab-resistant cell lines showed enriched proteins (CYTH1, SEC24D, VPS25, and ARFGAP3) involved in membrane trafficking, which is a pathway mediating many processes and enzyme functions that cancer cells can use to promote tumorigenesis and drug responses." (PMID 41301803, 2025).
VPS25 also shares sentences with these, for which no sentence is quoted: bladder tumor (1 paper); head and neck squamous cell carcinoma (1); lymph node metastasis (1); melanoma (1); type 2 diabetes mellitus (1).